HMGB1 (high mobility group box 1)
Diseases named in the same sentence as HMGB1 in open-access papers (continued):
Sharing a sentence is not in itself a finding about the gene and the disease.
Cognitive impairment (continued). "HMGB1 is a “late mediator” of inflammation, and excessive levels of HMGB1 may be involved in sustaining inflammation, with associated inflammatory tissue damage, organ dysfunction, and cognitive impairment." (PMID 35095387, 2021). "Previously, He at al. showed that HMGB1 may causes blood-brain barrier disruption leading to cognitive deficits in aged rats." (PMID 32622362, 2020). "However, whether MSCs-exo affects cognitive impairment in SAE through HMGB1-associated microglial pyroptosis and the molecular mechanisms are unclear." (PMID 38734709, 2024). "For example, Dex has been reported to attenuate neuroinflammation and cognitive impairment by suppressing HMGB1/RAGE/NF-κB signaling and to reduce apoptosis and improve tissue survival after ischemia/reperfusion injury via activation of PI3K/Akt and STAT3." (PMID 41473658, 2025). "Induction of HMGB1-mediated neuroinflammation following AIE is associated with reductions of basal forebrain cholinergic neurons and cognitive deficits in adulthood." (PMID 40046779, 2025). "Blocking HMGB1 release with minocycline significantly improved cognitive deficits in depressive models." (PMID 38826566, 2024). "Under pathological conditions, HMGB1 can enhance the phagocytosis of microglia, leading to overexpression of inflammatory mediators, abnormal synaptic pruning, neuronal dysfunction, and cognitive impairment." (PMID 38826566, 2024). "MSCs-exo-mediated delivery of miR-1403p ameliorates cognitive impairment in mice with SAE by HMGB1-related microglial pyroptosis and S-lactoylglutathione metabolism." (PMID 38734709, 2024). "In a study on AD mice, activation of the SIRT3 signaling pathway inhibited acetylation of HMGB1 induced by Aβ25-35, thereby restoring redox balance and inhibiting neuroinflammation, rescuing cognitive impairment in AD." (PMID 39091611, 2024). "In vitro and in vivo data showed that MSCs-exo-mediated delivery of miR-140-3p inhibited the neuroinflammatory response and pyroptosis by targeting Hmgb1 and improved cognitive impairment in CLP mice." (PMID 38734709, 2024). "In conclusion, we propose ROS/RNS, HMGB1, and sRAGE as stress biomarkers capable of predicting cognitive impairment in AUD patients." (PMID 38535924, 2024). "CLP-induced cognitive impairment was accompanied by increased HMGB1 secretion and microglial activation." (PMID 36906561, 2023). "In the present study, we showed that in SAE mice, HMGB1 mediates microglial activation and induces excessive phagocytosis of synapses and neuron dysfunction, ultimately leading to cognitive impairment." (PMID 36906561, 2023). "The area under the ROC curve for HMGB1 predicting cognitive impairment in patients with CMBs was 0.807 (P < 0.001)." (PMID 37424630, 2023). "By preventing brain inflammation and AD-like pathology through HMGB1 neutralization, GA has been found to protect mice from surgery-induced cognitive impairments (short swimming latency and distance in the MWM test)." (PMID 36950127, 2023). "Receiver Operating Characteristics (ROC) curves were used to assess the predictive value of HMGB1 for the occurrence of cognitive impairment in patients with CMBs." (PMID 37424630, 2023). "ROC curve analysis of the predictive value of HMGB1 showed that HMGBI had a high predictive value for the development of cognitive impairment in patients with CMBs, and the area under the ROC curve was 0.807 (95% CI:0.683- 0.931, P < 0.001)." (PMID 37424630, 2023). "In an animal model of AD, HMGB1 induced cognitive impairment through the Sirtuin 3/superoxide dismutase 2 signaling pathway." (PMID 36906561, 2023). "Consistent with our data, HMGB1 release induces cognitive deficits in diabetes-related dementia and TBI." (PMID 36906561, 2023). "In the meantime, it is widely accepted that HMGB1 release mediates hippocampal inflammation and contributes to cognitive impairment in preclinical models." (PMID 36552192, 2022).
Cognitive impairment (continued). "The knockout of MMP-9 rescues cognitive impairment and cisplatin-induced upregulation of HMGB1 in SHSY5Y cells." (PMID 35624958, 2022). "Current studies have demonstrated that HMGB1 plays an important role in inducing neuroinflammation and cognitive impairment in SAE." (PMID 36552192, 2022). "When HMGB1 concentration was examined, it was higher in patients at the stage of mild cognitive impairment (MCI) than in patients at full AD stage." (PMID 33876503, 2021). "We next examined the effect of the HMGB1 inhibitor GZ on cognitive disorders in the delayed period following virus injection." (PMID 34539383, 2021). "For instance, prolonged increase in HMGB1 is associated with cognitive impairment in intensive care unit survivors, suggesting that HMGB1 is an important factor that exacerbates the progression of cognitive impairments." (PMID 34539383, 2021). "By using the NLRP3-knockout TBI model, we found that the continuous activation of the NLRP3 inflammasome and high mobility group box 1 (HMGB1) release were closely related to cognitive impairment." (PMID 34666797, 2021). "In conclusion, inhibiting HMGB1 that stops self-reinforcing vicious loop from the NLRP3 inflammasome is a perspective treatment strategy of cognitive impairment after TBI." (PMID 34666797, 2021). "Inhibition of HMGB1 interrupts this vicious loop and will be an effective treatment for cognitive impairment after TBI." (PMID 34666797, 2021). "As such, icv HMGB1 treatment improved cognitive impairments and neurogenesis in a mouse model of Alzheimer’s disease." (PMID 34208101, 2021). "HMGB1 antibody inhibits neurite degeneration in the presence of Aβ plaques and recovers cognitive impairment in mice." (PMID 33946401, 2021). "The authors used neutralizing HMGB1 antibodies to inhibit memory impairments and i.p. daily injection of 500 μg HMGB1 for three weeks to induce cognitive impairments." (PMID 34208101, 2021). "Here, we report that BAI activated silent information regulator 1 (SIRT1) to deacetylate high-mobility group box 1 (HMGB1) protein in response to acute LPS-induced neuroinflammation and cognitive deficits." (PMID 33029280, 2020). "Among the DAMPs, high mobility group box 1 (HMGB1) is the most studied as it has been described in preclinical models of cognitive impairment." (PMID 32973455, 2020). "The anti-HMGB1 mAb treatment in 5xFAD mice ameliorated cognitive impairment at a similar level to WT mice." (PMID 32046119, 2020). "Higher numbers of NDEVs have also been found in the plasma of PLWH with cognitive impairment and were found to be enriched in high-mobility group box 1 (HMGB1), neurofilament-light (NF-L), and Aβ." (PMID 32784383, 2020). "This is the first study to demonstrate that HMGB1 significantly contributes to cognitive impairment at the chronic phase of CCH, partly through inflammation modulation." (PMID 32245271, 2020). "High-mobility group box 1 (HMGB1), also known as an alarmin protein, has been implicated as a critical factor involved in ischemia–reperfusion injury, mood disorder, cognitive impairment, and inflammation-related diseases in the CNS." (PMID 31695615, 2019). "Anti-HMGB1 mAb has ameliorated the symptoms and phenotype of AD in an experimental model where mAb against HMGB1 completely rescued cognitive impairment in a mouse model via inhibiting neurite degeneration even in the presence of amyloid beta (Aβ) plaques." (PMID 30271319, 2018). "Subcutaneous injection of anti-HMGB1 monoclonal antibody inhibits neurite degeneration, stabilizes spines, and improves cognitive impairment in AD model mice." (PMID 27557632, 2016). "Subcutaneous injection of a newly developed monoclonal antibody against HMGB1 strongly inhibits neurite degeneration even in the presence of Aβ plaques and completely recovers cognitive impairment in a mouse model." (PMID 27557632, 2016).
Cognitive impairment (continued). "Previous studies have shown increased concentration of protein levels of systemic S-100β and HMGB-1, and their pivotal role in surgery-induced cognitive deficits." (PMID 26225860, 2015). "In summary, this study identifies key mechanisms by which the RAGE pathway modulates microglial responses during HAHH, suggesting that targeted inhibition of HMGB1–RAGE signaling may attenuate HAHH-associated inflammation and cognitive deficits." (PMID 41009351, 2025). "RAGE and HMGB1 inhibitors may serve as novel therapeutic strategies to mitigate HAHH-induced cognitive impairment, providing a theoretical basis for the treatment of cognitive impairment." (PMID 41009351, 2025). "In this study, our objective is to confirm whether the HMGB1-RAGE axis is linked to HAHH-induced inflammation and cognitive impairment and to assess therapeutic efficacy of inhibition of the HMGB1-RAGE axis." (PMID 41009351, 2025). "Patients who developed cognitive impairment had significantly higher initial HMGB1 levels." (PMID 38708343, 2024). "rTMS may exert neuroprotective effects by counteracting the release of HMGB1, thereby ameliorating cognitive impairment." (PMID 38826566, 2024). "Our study demonstrated that increased HMGB1 secretion induces microglial activation, which in turn induces abnormal synaptic elimination and neuronal dysfunction in the hippocampus, ultimately leading to cognitive impairments in SAE mice." (PMID 36906561, 2023). "Notably, inhibiting HMGB1 secretion reverses these aberrant changes and ameliorates cognitive impairment in SAE mice." (PMID 36906561, 2023). "The study investigated the correlation and predictive value between the severity of cerebral microbleeds (CMBs) and the level of serum High Mobility Group Protein B1 (HMGB1) and the occurrence of cognitive impairment in patients with cerebral small vessel disease (CSVD)." (PMID 37424630, 2023). "Notably, some animal studies have found that surgery and anesthesia increased not only peripheral HMGB1 levels but also HMGB1 expression in the hippocampus in conjunction with the development of cognitive deficits." (PMID 37106766, 2023). "Mounting evidence suggests that high mobility group box-1 protein (HMGB1) plays a pivotal role in neuroinflammation and SAE, yet the mechanism by which HMGB1 induces cognitive impairment in SAE remains unclear." (PMID 36906561, 2023). "Our pilot findings suggest that sCD14, but not HMGB-1, LPS and d-lactate expression is associated with cognitive impairment in GCT survivors." (PMID 37025582, 2023). "Intervention targeting the HMGB1/TLR4/NF-κB pathway could alleviate neuroinflammation and improve cognitive impairment in models of depression, cognitive impairment caused by high-fat and high-sugar diets, and traumatic brain injury." (PMID 36552192, 2022). "Blocking HMGB1/RAGE signaling by Berberine also alleviates SAE’s cognitive deficits." (PMID 36552192, 2022). "Lipopolysaccharide (LPS) and high-mobility group box 1 (HMGB1) are Toll-like receptor (TLR4) agonists that activate proinflammatory neuroimmune signaling linked to loss of basal forebrain cholinergic neurons (BFCNs) and cognitive deficits." (PMID 36072299, 2022). "nEVs containing the neurotoxic proteins amyloid beta (Aβ), neurofilament light (NFL), p-T181-tau, and/or the inflammatory protein HMGB1 have been isolated from individuals with HIV cognitive impairment, Alzheimer’s disease (AD), and traumatic brain injury (TBI)." (PMID 33668514, 2021). "Moreover, we generated a new mouse monoclonal antibody against HMGB1 and revealed that administration of the antibody before the onset ameliorated cognitive impairment at the time point from onset and one month later." (PMID 33876503, 2021). "Inhibition of HMGB1 through oral pretreatment of glycyrrhizin was found to prevent postoperative cognitive impairment in aged mice, suggesting that HMGB1-mediated neuroinflammation may play a role in memory impairment." (PMID 33946401, 2021).
Cognitive impairment (continued). "Thus, although HMGB1 has been identified as a critical immune mediator in alcohol abuse, there is a need to further investigate other mechanisms underlying RAGE activation in abstinent AUD patients with cognitive impairment." (PMID 38535924, 2024). "Therefore, we hypothesized that HMGB1 secretion mediates microglial activation, aberrant synaptic pruning, and neuronal dysfunction, ultimately leading to cognitive impairment in SAE mice." (PMID 36906561, 2023). "However, the specific mechanism by which HMGB1 results in cognitive impairment in SAE remains unclear." (PMID 36906561, 2023). "In this study, HMGB1 was obviously increased in the hippocampus and PFC, regions tightly associated with spatial cognition, suggesting that HMGB1 may act as a detrimental downstream factor of p-tau in the cognitive impairment caused by tau overexpression." (PMID 34539383, 2021). "Therefore, inhibition of p-NR1 (Ser896) levels by HMGB1 may mediate NLRP3 inflammasome-induced cognitive impairment." (PMID 34666797, 2021). "However, HMGB1 is closely related to cognitive impairment in the chronic period after injury." (PMID 34539383, 2021). "Moreover, the reduced HMGB1 was accompanied by decreases in p-tau levels after the treatment, which may account for the beneficial effects of the GZ treatment on cognitive impairments." (PMID 34539383, 2021). "In this study, the alteration of NLRP3 levels was not obvious, but the NLRP3 inflammasome was activated 7 m post injection, and cognitive impairment appeared, indicating that it may be a major contributor to the elevation in HMGB1 and abnormal cognition resulting from tau overexpression." (PMID 34539383, 2021). "Moreover, TLR4 activation modulates NMDAR subunits through HMGB1 signaling, suggesting that neuroinflammation may be critical in mediating the cognitive deficits." (PMID 27822212, 2016). "The combined detection of HMGB1, NFL, and Aβ in plasma NDEs can specifically distinguish individuals with cognitive impairment." (PMID 40809518, 2025). "Limited binding of HMGB1 and MD-2 downregulates the expression of NLRP3, thereby alleviating neuroinflammation and cognitive impairment in CLP model mice." (PMID 38734709, 2024). "In this study, we showed that the delivery of miR-140-3p by MSCs-exo ameliorated cognitive impairment in CLP mice by improving microglial pyroptosis and S-lactoylglutathione metabolism by targeting Hmgb1." (PMID 38734709, 2024). "In our study, we demonstrated that the expression of n-HMGB1 was significantly decreased in the hippocampus after CLP, while ICM treatment inhibited HMGB1 secretion and reduced cognitive impairment." (PMID 36906561, 2023). "However, the mechanism by which HMGB1 induces cognitive impairment in SAE remains unclear." (PMID 36906561, 2023). "HMGB1 induces microglial activation, aberrant synaptic pruning, and neuron dysfunction in an animal model of SAE, leading to cognitive impairment." (PMID 36906561, 2023). "The cognitive impairment was induced by using cigarette smoke exposure and treatment with GLP-1 stimulator considerably decreased HMGB1 in cigarette smoke exposed rats." (PMID 36364135, 2022). "In doxorubicin (DOX)-impaired rats, galangin significantly mitigates cognitive impairment and neurotoxicity via the NOX-1/Nrf-2/HMGB1/TLR4 and TNF-α/MAPKs/RIPK/MLKL/BDNF pathways." (PMID 36015161, 2022). "We previously reported that nEV HMGB1 and NFL were elevated in HIV-infected individuals with cognitive impairment." (PMID 33668514, 2021). "In this study, both the HMGB1 inhibitor and the NLRP3 knockout markedly alleviated cognitive deficits." (PMID 34539383, 2021). "Our data showed that the NLRP3 inflammasome continues to be activated along with high HMGB1 levels in the model at 4–8 weeks after TBI, which is consistent with cognitive impairment and LTP inhibition." (PMID 34666797, 2021).
Cognitive impairment (continued). "Thus, HMGB1 and its proinflammatory cytokines may contribute to neuronal loss and cognitive impairment, as shown by hippocampal atrophy and NOR test, respectively." (PMID 32245271, 2020). "In recent days, more attention has been paid to HMGB1 due to its contribution in traumatic brain injury (TBI), neuroinflammatory conditions, epileptogenesis, and cognitive impairments and has emerged as a novel target for those conditions." (PMID 30271319, 2018). "In rats, alcohol exposure during adolescence activates HMGB1/TLR4 danger signaling in the brain, and this activation persists into adulthood correlating with the presence of cognitive deficits." (PMID 30687006, 2018). "Whether HMGB1 acts upstream of RAGE and whether the HMGB1-RAGE axis plays a key regulatory role in HAHH-induced inflammation and cognitive impairment remain unclear." (PMID 41009351, 2025). "They further found that OBB or OBB‐NC administration can reduce long‐term neuropsychiatric complications such as anxiety, depression, and cognitive impairment, as well as inhibit the HMGB1‐mediated TLR4/NF‐κB pathway in microglia by downregulating the levels of TLR4, HMGB1, NF‐κB, TNF‐α and IL‐6." (PMID 40824273, 2025). "HMGB1 is a nuclear protein that promotes inflammation and we reported an increase in this protein previously with nEVs from nLongC individuals and in HIV-infected individuals with cognitive impairment." (PMID 38534322, 2024). "It is reasonable to speculate that HMGB1 inhibitors would be most effective prior to the onset of severe pathologies, such as in APOE4 patients with mild cognitive impairment." (PMID 37863057, 2023). "Furthermore, HMGB1 neutralization has been shown to reduce cognitive dysfunction and post-TBI cognitive impairment." (PMID 36950127, 2023). "Schizophrenia and affective disorders have been found to share a common pathogenesis (related to IL-6, CCL11, HMGB1, DKK1 and KOR), which may explain, at least in part, the symptoms and cognitive impairment observed in these disorders." (PMID 37298365, 2023). "Patients with cognitive impairment had significantly higher levels of HMGB1, UA, and HbAlc than the group without cognitive impairment (P < 0.05)." (PMID 37424630, 2023). "For example, recent studies found that Aβ-induced increases in HMGB1 levels in experimental animals or cultured microglial cells, but therapy targeting Aβ was not always effective in cognitive disorders." (PMID 34539383, 2021). "The protective effects of BAI on cognitive impairment in mice appeared to be related to its anti-inflammatory activity in microglial cells, modulating the activity of SIRT1, as well as downregulating the HMGB1 signaling pathway." (PMID 33029280, 2020). "Therefore, we hypothesized that HAHH activates the HMGB1-RAGE axis in hippocampal microglia, driving neuroinflammation and cognitive impairment—a process reversible by RAGE inhibition." (PMID 41009351, 2025). "Taken together, our findings indicate that nonoxid-HMGB1 reduces TBI-mediated cognitive impairment." (PMID 35479959, 2022). "Subcutaneous or intravenous injection of human monoclonal anti-HMGB1-Ab #129 into 5xFAD mice suppressed MARCKS phosphorylation at Ser46 in immunohistochemistry and western blot analyses, recovered decrease of dendritic spines, and recovered cognitive impairment." (PMID 34635772, 2021). "Furthermore, nonoxid-HMGB1 ameliorated cognitive impairment in rats post-TBI via SH3RF2." (PMID 35479959, 2022). "Supposedly, HMGB1 serum levels may differ between ASD children with and without accompanying intellectual impairment." (PMID 34198762, 2021).